INS (insulin)
Diseases named in the same sentence as INS in open-access papers (continued):
Sharing a sentence is not in itself a finding about the gene and the disease.
MELAS (6 papers, 2011 to 2025). "DM develops into MELAS syndrome due to multiple defects in insulin and glucose metabolism, including insulin deficiency, increased gluconeogenesis, and insulin resistance in pancreatic β-cells; an ATP-sensitive potassium channel is required for insulin release." (PMID 36005129, 2022). "Five patients were initially treated with metformin; however, they were later switched to insulin therapy after their diagnosis of MELAS." (PMID 40382647, 2025). "For example, the methylene lipid group (CH2)n is linked to arterial stiffness, while the peak of the intramyocellular methylene (IMCL(CH2)n) is used as a biomarker for insulin resistivity and mitochondrial disorder MELAS." (PMID 35629890, 2022). "No adverse effect was observed in either trial except for hypoglycemic episodes in an insulin-treated MELAS patient, which subsided by reducing the insulin dose." (PMID 22146674, 2011).
myeloid leukemia (6 papers, 2009 to 2025). A clonal proliferation of myeloid cells and their precursors in the bone marrow, peripheral blood, and spleen. "Functional annotation analyses indicated that these DEGs were mostly significantly enriched in insulin signalling, myeloid leukaemia, and glucagon signalling pathways." (PMID 33596828, 2021). "Besides, the Insulin signaling pathway, Acute myeloid Leukemia Pathway, Regulation of actin cytoskeleton pathway and other biological pathways were also enriched in the high immune cell infiltration cluster (Nom p-value < 0.05)." (PMID 36211454, 2022).
myocarditis (6 papers, 2010 to 2025). Myocarditis is a condition that is characterized by inflammation of the heart muscle (myocardium). "In conclusion, this study indicates the potential role of impaired insulin signalling in the mechanism underlying inflammation-induced cardiac dysfunction, which suggests that the improvement of insulin signalling can be a target of treatment against myocarditis or DCMi." (PMID 31616027, 2019). "Considering the results found in this study, improvement of insulin signalling with anti-diabetic drugs might have a beneficial effect on cardiac dysfunction in myocarditis." (PMID 31616027, 2019).
nephrotic syndrome (6 papers, 2010 to 2026). A collection of symptoms that include severe edema, proteinuria, and hypoalbuminemia; it is indicative of renal dysfunction. "Literature data indicated that PLC ε is important for heart development, is involved in nephrotic syndrome, increases insulin secretion, and is highly expressed in the lung." (PMID 27026853, 2016). "After switching corticosteroids to cyclosporine in the boy with nephrotic syndrome and discontinuing corticosteroids in the girl with autoimmune haemolytic anaemia, both had an apparent decrease of insulin dose followed by the complete omitting of insulin treatment for more than 18 months." (PMID 37100887, 2023).
nosocomial infection (6 papers, 2020 to 2023). An infection acquired in a hospital or other healthcare setting. "Furthermore, irregular insulin injection procedures can increase the incidence of bleeding, pain, subcutaneous fat hyperplasia, and increase the risk of cross-infection, and affect the therapeutic efficacy of patients." (PMID 37501783, 2023).
pancreatic agenesis (6 papers, 2020 to 2026). Partial agenesis of the pancreas is characterized by the congenital absence of a critical mass of pancreatic tissue. "Insulin is a potent fetal growth factor and absent fetal insulin secretion in individuals with pancreatic agenesis results in greatly reduced birthweight (approximately −1400 g, SD 3)." (PMID 33029656, 2020).
personality disorder (6 papers, 2016 to 2026). A diverse category of psychiatric disorders characterized by behavior that deviates markedly from the expectations of the individual's culture; this pattern of deviation is pervasive and inflexible and is stable over time. "Although stopping insulin was an option, childhood/adolescent psychotic, depressive, and personality disorders necessitated antipsychotics." (PMID 40362174, 2025).
phobia (6 papers, 2014 to 2024). "Further psychological concerns may include the reluctance to initiate insulin or other injectable therapy because of an exacerbated phobia of injection pain or due to misconceptions that associate the administration of insulin with treatment failure." (PMID 39057600, 2024). "CSII is often initiated in pre-school children due to their and their families’ needs related to unpredictable food patterns, low insulin requirements, reduction in the number of injections, ease of insulin delivery and needle-phobia, which helps explain why CSII is used more by younger people." (PMID 32576284, 2020). "BII phobia is considered in some cases to have severe and may even become life threatening when essential medical procedures such as urgent surgery, blood transfusion, or insulin injections cannot be delivered." (PMID 25049451, 2014). "A literature review abstract which searched articles related to prevalence of needle fear, needle phobia, injection fear or blood-injury-injection phobia suggested needle fear affects 28% of patients receiving insulin injections, however no details of assessment methods were included." (PMID 34111207, 2021).
Pruritus (6 papers, 2014 to 2024). Pruritus is an itch or a sensation that makes a person want to scratch. "The study raised some concerns, however, since it induced pruritus in almost one-fourth of the patients, worsened insulin resistance and lipid profile with an increase in total and LDL-cholesterol, and a decrease in HDL-cholesterol." (PMID 38146424, 2023). "In our study, the complaint of pruritus was significantly higher in the mixed insulin or basal-bolus insulin treatment group at a rate of 46.5% (p = 0.032)." (PMID 38813039, 2023). "A single ADR was reported in the insulin detemir group (pruritus, skin and subcutaneous tissue disorder), and the relationship of this ADR to insulin detemir was determined as ‘probable’." (PMID 25048824, 2014).
psoriatic arthritis (6 papers, 2012 to 2021). Joint inflammation associated with psoriasis. "One report showed that chronic treatment with infliximab for either RA or psoriatic arthritis brought about a substantial improvement in insulin sensitivity." (PMID 22234148, 2012).
Rabson-Mendenhall syndrome (6 papers, 2013 to 2024). Rabson-Mendenhall syndrome belongs to the group of extreme insulin-resistance syndromes (which also includes leprechaunism, the lipodystrophies, and the type A and B insulin resistance syndromes). "Rabson-Mendenhall syndrome (RMS) is a rare autosomal recessive disorder characterized by severe insulin resistance, a condition in which the body's tissues and organs do not respond appropriately to the hormone insulin." (PMID 33728143, 2021). "These conditions, Donohue syndrome (leprechaunism) and Rabson-Mendenhall syndrome, include growth impairment and short stature and illustrate the important roles of insulin in both linear growth and regulating blood glucose." (PMID 33210059, 2020).
rectal cancer (6 papers, 2005 to 2024). A primary or metastatic malignant neoplasm that affects the rectum. "Considering this prominent role of insulin in rectum cancer, it can be concluded that the factors which increase insulin biosynthesis and secretion indirectly are involved in rectum cancer promotion." (PMID 30774817, 2018).
retinal disease (6 papers, 2013 to 2025). "At the molecular level, insulin modulates the expression of key proteins, including upregulation of the IR β subunit, and influences factors implicated in retinal diseases." (PMID 41301488, 2025). "Despite these challenges, the concept of RPE-derived insulin provides a novel perspective on retinal self-regulation and offers a potential metabolic strategy for early intervention in retinal diseases." (PMID 41301488, 2025). "Our results suggest that insulin may serve as a viable treatment option to preserve visual function, likely through its metabolic support of neuroretinal cells, which are often compromised in various retinal diseases." (PMID 40733109, 2025). "Nevertheless, it should be noted that, on the one hand, the insulin signaling pathways are complex, and on the other hand, current prospective studies regarding the role of improving IR in the management of certain retinal diseases are relatively lacking." (PMID 38952394, 2024). "Similarly, in a study on 585 T2DM patients without exogenous insulin, the greater baseline insulin levels and C-peptide are correlated to the development of retinal disease." (PMID 37959313, 2023).
Salmonella Infections (6 papers, 2018 to 2023). Infections with bacteria of the genus SALMONELLA. "Notably, two human diseases related pathways, insulin resistance and Salmonella infection were enriched." (PMID 30081495, 2018). "In our results, Salmonella infection resulted in a decrease in piglet GLP-1 secretion and a decrease in insulin levels." (PMID 35163196, 2022). "In the primiparous vs. multiparous group, it is mainly concentrated in signaling pathways such as postpartum disease, such as Salmonella infection, AMPK signaling pathway, Transcriptional misregulation in cancer, and the Insulin signaling pathway." (PMID 36140838, 2022).
SHORT syndrome (6 papers, 2016 to 2025). A rare disorder characterized by multiple congenital anomalies, including short stature, hyperextensibility of joints, ocular depression, Rieger anomaly and teething delay in which the cause of the disease is a mutation in PIK3R1 gene. "In contrast, mutation in insulin signalling causing the SHORT syndrome (PI3K) affects very immediate post-receptor steps of insulin signalling." (PMID 31583022, 2019). "This demonstrates that the effect of this SHORT syndrome PIK3R1 mutation on insulin signaling is cell type specific." (PMID 27766312, 2016). "Attenuated insulin-induced association of p110α with Irs1 in the presence of activating p110 delta syndrome 2 (APDS2) and SHORT syndrome mutant p85α." (PMID 39835783, 2025). "Attenuated insulin-induced association of p110α with Irs2 in the presence of activating p110 delta syndrome 2 (APDS2) and SHORT syndrome mutant p85α." (PMID 39835783, 2025). "SHORT syndrome is caused by mutations in PIK3R1; encoding components of the insulin signalling enzyme phosphoinositide 3-kinase (PI3K)." (PMID 32439336, 2020). "This potential explanation for the unusual IR subphenotype of SHORT syndrome warrants testing in humans with SHORT syndrome or other proximal insulin signalling defects." (PMID 32439336, 2020). "We report 5 patients with SHORT syndrome and C-terminal mutations in PIK3R1, encoding the p85α/p55α/p50α subunits of PI3K, which act between INSR and AKT in insulin signaling." (PMID 27766312, 2016). "A critical insight from the study of SHORT syndrome was that the insulin signalling role of PIK3R1 could be severely attenuated by neomorphic mutations disrupting the C-terminal SH2 domain." (PMID 32439336, 2020). "Besides often being insulin resistant, SHORT syndrome patients with mutations in PIK3R1 do not exhibit fatty liver." (PMID 37628845, 2023). "Blunted insulin signalling in 3T3-L1 preadipocyte models of activating p110 delta syndrome 2 (APDS2) and SHORT syndrome." (PMID 39835783, 2025).
Sjögren’s syndrome (6 papers, 2015 to 2025). "Only a maternal age of above 40 years, lower 1-min Apgar score, and female sex were associated with residual GAA and insulin-treated GDM in a previous pregnancy and maternal Sjögren’s syndrome were associated with residual GAD." (PMID 28503212, 2017). "Furthermore, our findings show that DNAm GAD was associated with insulin-treated GDM in a previous pregnancy and Sjögren’s syndrome." (PMID 28503212, 2017). "When based on the DNAm GA residual, GAA was associated with a maternal age of above 40 years at delivery, and GAD with insulin-treated GDM in a previous pregnancy and maternal Sjögren’s syndrome." (PMID 28503212, 2017). "For example, the application of insulin for T1DM patients to maintain blood glucose homeostasis or the use of tear and saliva replacements as the main treatment of Sjögren’s syndrome (SS) patients, accompanied by supplemental medications to address additional complications." (PMID 34572503, 2021).
skin infection (6 papers, 2012 to 2023). An inflammatory process affecting the skin, caused by bacteria, viruses, parasites, or fungi. "Twenty-nine children (69%) had insulin-pump problems in the form of skin irritation (31%), skin infection (7.1%) and pump Set/Site occlusion (31%)." (PMID 38012643, 2023). "None of the studied children reported problems with the availability of pump supplies, whereas twenty nine children (69%) had insulin pump problems in the form of skin irritation (31%), skin infection (7.1%) and pump Set/Site occlusion (31%)." (PMID 38012643, 2023). "NET formation induced by S. aureus has been shown to worsen skin infections, thus a reduction of NET formation by insulin may be beneficial for healing." (PMID 37626968, 2023).
spinocerebellar ataxia (6 papers, 2014 to 2025). "Previous studies have shown that homozygous staggerer mice are leaner and display improved insulin sensitivity but also have a severe cerebellar ataxia." (PMID 28744254, 2017). "Abnormalities in the insulin/insulin-like growth factor 1 (IGF-1) system (IIS) signalling pathway were thought to play a role in the physiopathological processes of various neurodegenerative disorders, including spinocerebellar ataxias." (PMID 26331034, 2014).
squamous cell carcinoma (6 papers, 2013 to 2025). A carcinoma arising from squamous epithelial cells. "Specifically, deregulation of the TGF-beta, VEGF, mTOR, Wnt, Hedgehog and insulin signaling pathways has been found to be associated with aggressive disease in squamous cell carcinomas." (PMID 23950933, 2013). "The amount of surface-expressed β2AR lost to internalization in response to insulin in HEK-293, ∼15%, correlated well with results obtained in DT1MF-2 smooth muscle cells and CHO cells but was smaller than the reported value of ∼30% in epidermoid carcinoma A431 cells." (PMID 25401701, 2014).
Thromboembolism (6 papers, 2017 to 2025). The formation of a blood clot inside a blood vessel that subsequently travels through the blood stream from the site where it formed to another location in the body, generally leading to vascular occlusion at the distant site. "The pathophysiological mechanisms underlying the possible association between insulin therapy and AF-related thromboembolism in diabetic patients are not completely known." (PMID 32471222, 2020). "It is very easy to overlook the re-dosing of antibiotics, the administration of insulin, venous-thromboembolism prophylaxis and other clinically relevant therapies." (PMID 28435497, 2017).
thymoma (6 papers, 1990 to 2024). A neoplasm arising from the epithelial cells of the thymus. "PPARγ overexpression more than doubled insulin-stimulated thymoma viral protooncogene phosphorylation during low lipid availability." (PMID 34104648, 2021). "The degree of hyperinsulinaemia depended on the diet only in the thymoma-bearing mice, with linseed and fish oils producing higher insulin levels than soya-bean oil." (PMID 2124137, 1990). "Insulin administration to diabetic tumour bearing mice, enhanced 3H-thymidine incorporation in the thymoma tumour cells only, and the insulin content of the EL4 tumours was found to be higher than that of the thymoma tumours." (PMID 2186773, 1990). "Given the insulin-dependent nature of thymoma, it is resonable to believe that targeting cholesterol metabolism might provide a potential benifits to patients." (PMID 39434140, 2024).
transient neonatal diabetes mellitus (6 papers, 2010 to 2024). Transient neonatal diabetes mellitus (TNDM) is a genetically heterogeneous form of neonatal diabetes (NDM) characterized by hyperglycemia presenting in the neonatal period that remits during infancy but recurs in later life in most patients. "This locus, and overexpression of PLAGL1 specifically, has been associated with transient neonatal diabetes mellitus (TNDM) possibly by reducing insulin secretion." (PMID 30082726, 2018). "Transient neonatal diabetes mellitus (TNDM, OMIM#601410; prevalence at birth: 1:400,000) is defined as an insulin-requiring hyperglycemia appearing during the first six months of life." (PMID 32224912, 2020). "On the other hand, paternal duplication of the PLAGL1 locus is responsible for transient neonatal diabetes mellitus (TNDM) which has characteristics such as intrauterine growth retardation and hyperglycemia due to lack of normal insulin secretion." (PMID 33918057, 2021).
type B insulin resistance (6 papers, 2016 to 2025). "In addition, the total insulin dose was smaller than that reported in previous studies on type B insulin resistance." (PMID 27456688, 2016).
vasculitis (6 papers, 2016 to 2024). "Differentially expressed miRs may regulate neuroinflammation, cellular senescence and aging, glucose and lipid metabolism, insulin signaling pathways, vasculitis and thrombogenesis, and immune function." (PMID 38891870, 2024).
Visual impairment (6 papers, 2012 to 2024). "Visual impairment is associated with increased age, poor regular exercise, longer duration of DM, and insulin treatment." (PMID 35114950, 2022). "Visual impairment is associated with increased age, longer duration of DM, higher body mass index, lower educational level, and use of insulin as treatment option." (PMID 35114950, 2022). "Being elderly, relying on others for care, suffering from visual impairment and having irregular mealtimes also caused patients to hesitate over starting insulin." (PMID 22469132, 2012). "Indeed, examination of particular subgroups, including those with visual impairment or reduced manual dexterity or cognition, may help guide how best to pair glucose monitoring and insulin delivery modality to the needs of an individual." (PMID 37794113, 2023).
vitamin D (6 papers, 2013 to 2023). "Many in vitro studies suggest repletion of vitamin D insufficiency may improve insulin secretion and sensitivity." (PMID 27413370, 2016). "First, vitamin D insufficiency causes parathyroid hormone (PTH) to compensate for decreased calcium absorption, a response that leads to increased intracellular calcium, which may prevent insulin target cells from sensing the intracellular calcium fluxes necessary for insulin action." (PMID 25254046, 2014).
xerostomia (6 papers, 2014 to 2025). Dryness of the mouth resulting from reduced salivary secretion. "Moreover, patients receiving an anti-diabetic medication, consisting of insulin injection, reported more xerostomia [54(49.1%) vs. 80(33.5%); P = 0.005]." (PMID 24495383, 2014). "Another potential mechanism linking AMY1 CN to xerostomia could involve insulin resistance." (PMID 39953449, 2025). "Cluster 2 (labeled “Diabetic individuals”; n = 12) was characterized by older participants with the highest proportion of diabetic subjects (100%; 73% insulin users), lower BMI, higher DMFT index, OHIP-14, and xerostomia scores, and who reported having consumed fruit and vegetables the day before." (PMID 33330590, 2020). "A total of 27 (45%) individuals who used insulin and 32 (53.3%) individuals who did not use insulin reported moderate to severe xerostomia." (PMID 28767676, 2017). "The methodological heterogeneity and the lack of studies comparing salivary flow and xerostomia among diabetic groups–insulin-dependent and non-insulin dependent individuals–reveal the need for further studies on this issue." (PMID 28767676, 2017).